OGFOD2 (2-oxoglutarate and iron dependent oxygenase domain containing 2)
Synonyms: FLJ13491; FLJ37501
Tractability: PROTAC: ubiquitination databases record sites on it.
Gene: Protein-coding gene on chromosome 12 (122,974,580 to 122,980,043, forward strand). Ensembl gene ENSG00000111325.
Subcellular location (Human Protein Atlas): Nucleoplasm; Nuclear bodies
Gene Ontology:
Molecular function: iron ion binding; L-ascorbic acid binding; oxidoreductase activity, acting on paired donors, with incorporation or reduction of molecular oxygen
Cellular component: nuclear body; nucleoplasm
Genetic constraint (gnomAD): Loss-of-function variants: 29 observed, 28.43 expected, observed/expected ratio (o/e) 1.02, 90% interval 0.76 to 1.39. The upper end of that interval is the gene's LOEUF score, 1.39, which puts it in group 5 of 6, group 1 being the genes least tolerant of losing a copy. Missense variants: 437 observed, 405.96 expected, observed/expected ratio (o/e) 1.08, 90% interval 1 to 1.16. Synonymous variants: 204 observed, 182.18 expected, observed/expected ratio (o/e) 1.12, 90% interval 1 to 1.26.
Homologues: Orthologues: chimpanzee OGFOD2 (99% identical), macaque OGFOD2 (95% identical), pig OGFOD2 (89% identical), dog OGFOD2 (88% identical), rat Ogfod2 (87% identical), guinea pig OGFOD2 (85% identical), mouse Ogfod2 (85% identical), rabbit OGFOD2 (61% identical), tropical clawed frog ogfod2 (55% identical), zebrafish ogfod2 (53% identical). Paralogues in human: PTCD1 (15% identical).
Diseases named in the same sentence as OGFOD2 in open-access papers:
OGFOD2 is named in the same sentence as 9 diseases in open-access papers, as found by Europe PMC text mining. Sharing a sentence is not in itself a finding about the gene and the disease. The quoted sentences say what the papers report.
schizophrenia (3 papers, 2018 to 2024). A major psychotic disorder characterized by abnormalities in the perception or expression of reality. "Many genes that were found in this analysis, including CRHR1, ARL17A, NSF, and OGFOD2, have been implicated in previous GWAS of regional brain volumes, and have also been linked to brain disorders, including epilepsy, schizophrenia, and brain cancer." (PMID 39269986, 2024). "For schizophrenia, we looked at the expression of OGFOD2 and RORB in the cerebellum." (PMID 38671846, 2024).
kidney stone (1 paper, 2025). "Genes associated with the identified metabolites (e.g., CLDN10, OGFOD2, and GGT1) were found to have causal links to kidney stone formation." (PMID 40842671, 2025).
cancer (1 paper, 2021). A tumor composed of atypical neoplastic, often pleomorphic cells that invade other tissues. "On the other hand, CGI reported SRC as the only predicted cancer driver with an oncogenic function, whereas OGFOD2 and ZNF408 were annotated as passenger mutations." (PMID 33916261, 2021).
OGFOD2 also shares sentences with these, for which no sentence is quoted: brain cancer (1 paper); brain disorder (1); calculus (1); epilepsy (1); Hypertension (1); insomnia (1).